IL2 (interleukin 2)
Diseases named in the same sentence as IL2 in open-access papers (continued):
Sharing a sentence is not in itself a finding about the gene and the disease.
infection (continued). "Interestingly, following D22 (ICP22 null) infection, cytokine levels increased to equal those following KOS infection for the following infiltrates: CD8+IL-2+ (18.3% vs. 16.9%), CD8+perforin+ (0.6% vs. 0.6%), and CD8+CD25− (5.4% vs. 2.7%)." (PMID 31387116, 2019). "IL-2 levels significantly decreased at 6 h after infection, increased significantly at 3–6 dpi, and were not significantly different at 30 h; IL-4 levels were increased from 3 dpi to 6 dpi." (PMID 31855175, 2019). "In addition, the levels of pro-inflammatory cytokines (IL-2, IL-6, IL-12, TNF-α, IFN-α, IFN-γ) were higher in il10−/− mice than in wild-type mice at 1, 3, and 6 h post infection." (PMID 31551984, 2019). "When IL-2 is no longer available, such as when the infection is resolved, exosomes can no longer affect low-affinity CTLs." (PMID 31275303, 2019). "25-HC improved the overall IFN-γ-producing cellular responses which are beneficial for controlling HIV-1 replication, but selectively suppressed IL-2/TNF-α-producing proinflammatory CD4+ T cells which are helpful for reducing inflammation and infection targets of HIV-1." (PMID 30524435, 2018). "On one hand, proinflammatory cytokines (e.g., IL-1α, IL-2, and TNF-α) are necessary to initiate the inflammatory response during infection, but the overexpression of such cytokines may lead to pathological responses." (PMID 30627122, 2018). "A low level of secreted IL-2 after infection is both safe and efficacious, but the lack of control of IL-2 expression in vivo can lead to toxicity." (PMID 30410056, 2018). "Therefore, the expression of IL-2 was increased after treatment, especially in SAT + AT group, which enhanced host immunity against infection, accelerated clearance of polypide, and inhibited parasite growth." (PMID 29785189, 2018). "At later timepoints following infection (weeks 16 and 22), therapeutic immunization induced a significantly higher frequency of CD4+ T cells producing CD154, GM-CSF, IFN-γ, IL-2, and TNF-α at 16 and 22 weeks post infection compared to RHZ-treated mice with ex vivo ID93 antigen stimulation." (PMID 29795025, 2018). "However, we do observe CD154, IFN-γ, IL-2, and TNF expression from the RHZ+ID93/GLA-SE groups as early as seven weeks post infection." (PMID 29795025, 2018). "Consistent with the pro-proliferative role of IL-2, terminally differentiated effector CD8 T cells (SLECs) that express IL-2Rα for longer duration during an acute infection expand more than their memory-fated counterparts (MPECs) that downregulate the expression of IL-2Rα earlier." (PMID 30619342, 2018). "Following infection, cells were driven into quiescence through gradually decreasing concentrations of IL-2, and at day 12 post infection, HSA was no longer detectable on the surface of infected cells (lane 2)." (PMID 30475902, 2018). "It is plausible that curtailed or weak IL-2 signals drive lower levels of STAT-5, Akt and mTOR activity, thus resulting in lesser proliferation, effector differentiation and trafficking to peripheral sites of infection." (PMID 30619342, 2018). "Similarly, and suggestive of either exposure to M. leprae antigens or even low level infection due to their contact with their index case, whole blood from HHC also secreted IFN-γ and IL-2 following incubation with PPD and MLCS." (PMID 30631322, 2018). "Interestingly, only three cytokines increased in levels throughout duration of infection: IL-2, IL-4, and TNFα, the latter being important for DENV-3 C0360/94 infection of AG129 mice." (PMID 29559699, 2018). "However, although P. vivax and P. falciparum malaria patients have similar cytokine profiles during infection, P. falciparum patients presented higher levels of IFN‐γ, TNF‐α, and IL‐2 in acute phase than P. vivax." (PMID 29314720, 2018).
infection (continued). "The role of CD8 T cells during infection for protection has been also recently investigated, with CD8 T cells that produce IFN-γ and TNF-α enhancing cytolytic activity and secreting IL-2 to promote cell expansion that could enhance CD8 T cell memory function." (PMID 30631322, 2018). "During infection, MG interacts with host respiratory epithelial cells and generates an inflammatory response, resulting in increased levels of cytokines, such as tumor necrosis factor alpha (TNF-α), interleukin-6 (IL-6), and interleukin-2 (IL-2)." (PMID 29652844, 2018). "Regarding TH1 cytokines, IL-2 was not induced in WT or IL-33 KO mice after L2-MHV3 infection at mRNA level in the liver, neither at protein level in mouse sera (data not shown)." (PMID 28607531, 2017). "We propose that suppression of GFAP on astrocytes in the absence of macrophages or in the presence of IL-2 following infection with HSV-1 affect IL-12p70 expression thus leading to autoreactivity of T cells and thus CNS demyelination." (PMID 28542613, 2017). "We feel that these contrasting results most likely stem from the infection of HSV-1 in the presence of IL-2 over-expression or in the absence of macrophages in our two models of MS." (PMID 28542613, 2017). "In fact, the T cell anergy observed during these infections is characterized by a lack of cytokine responses and reduced proliferative activity, which can be reversed by the addition of IL-2 and results in a reduction of GRAIL expression." (PMID 28114324, 2017). "While the expression levels of IL-2 and IL-4 in calcitriol treated mice were a slightly higher following infection than in untreated mice at days 4 to 6 post-infection, there were no marked differences between the three groups." (PMID 28114957, 2017). "Finally, similar to eSF-mediated enhancement of NLENG1I, eSF enhanced BaLGFP and THROGFP infection of purified CD4+ T cells, and efficient enhancement was observed with T cells activated through either PHA/IL2- or anti-CD3/CD28." (PMID 28207890, 2017). "In the contrast with non-fractionated dosing regimens, we also found much higher IL-2 levels in mammary glands with the 25 and 50 μg cefquinome/gland in the 12 h interval groups suggesting a more severe infection for these mice." (PMID 28824576, 2017). "IL-2 and IFN-γ levels in the rEg.P29 group increased statistically compared with that in PBS or FCA groups (P < 0.01) at week 6 (2 weeks after the boost immunization) and then sequentially increased at week 9 (1 week after the infection)." (PMID 27094043, 2016). "A few cytokines were shown to have no distinguished trend or increases following infection: GM-CSF, IL-2, IL-12, and IL-4." (PMID 27043611, 2016). "Starting from the first day of severe infection caused by 103 PFU Absettarov strain, no TNF-α or IL-2 were detected in sera of infected mice." (PMID 28163697, 2016). "After 60 h of infection, at the more acute phase, the bacteria had induced a substantial increase in the expression of genes for most proinflammatory cytokines, including IFN-γ, IL-1β, IL-2, IL-6, IL-8, IL-22, and TNF-α, as well as genes for IL-10 and IL-4." (PMID 27357336, 2016). "In determining the percentages of CD4+T-cells that produced IL-2, the mice immunised with mc2-CMX and BCG hadsignificantly higher levels than the PBS group, but only the mc2-CMX hadsignificantly higher levels when compared to the infection group." (PMID 27074251, 2016). "Non-egg or low egg intensity infections (SmPCR+) on the other hand revealed a unique profile of elevated SEA-specific IgG4 with decreased systemic IL-2 and IL-1β." (PMID 27152725, 2016). "Infection with pathogens that induce TH1 CD4+ lymphocytes and secrete interferon gamma (IFNg) and interleukin-2 (IL-2) can be compared to induction of the TH2 response following schistosome infection or exposure to parasite eggs or egg antigen resulting in the production of IL-4, IL-5, and IL-13." (PMID 26741130, 2016).
infection (continued). "As with the analyses based on virus strain, stimulation with MoDC + inactivated virus had no significant impact on IFN-γ or IL-2 production, while infection with MoDC + live virus resulted in increased percentages of cytokine-producing T cells." (PMID 27191161, 2016). "METH did not alter the expression pattern of IL-2/IFN-γ/TNF-α in the CD8 T cells during the entire course of infection." (PMID 27760221, 2016). "Thus, BCG vaccination alters the ensuing polyfunctional profile upon infection with virulent M. bovis, favoring early IFN-γ/TNF-α/IL-2 production by CD4+ Tcm cells and dampening TNF-α/IFN-γ elicited by infection." (PMID 27799930, 2016). "On the other hand, the expression of il2 and il4 was below the detection limit in all tissues at any time point irrespective of infection." (PMID 26146835, 2015). "The signature also performed better than a wide range of host-proteins with an established role in the immune response to infection, including bacterial-related (e.g. TREM, IL-6 and IL-8), virus-related (e.g. IFN-γ and IL-2), and inflammation-related (e.g. IL-1a and TNF-α) proteins (P<10–8)." (PMID 25785720, 2015). "Based on transcriptional analysis studies, infection with virulent strains of NDV induces transcriptional upregulation of numerous cytokines, such as interferon alpha (IFN-α), interferon gamma (IFN-γ), interleukin 8 (IL-8), and interleukin 2 (IL-2)." (PMID 26253150, 2015). "Functional differences between Tem and Tcm subsets also have been demonstrated, with Tcm having a greater capacity to produce IL-2, increased proliferative potential, and the ability to provide increased protection following some, but not all infections." (PMID 26485703, 2015). "Early during infection, TGF-β signaling suppressed the expression of the high affinity IL-2 receptor α chain (CD25) on virus-specific CD4 T cells, which tempered IL-2 signaling and STAT5 and mammalian target of rapamycin (mTOR) activation in Tfh precursor CD4 T cells." (PMID 25569154, 2015). "Some functions of memory CD8 T cells analyzed on the population level, such as ability to produce IL-2, increased with time after infection, but were no different in CD62Lhi memory cells early or late after infection." (PMID 26485703, 2015). "To investigate whether mAb 2c treatment influences the secretion of IFN-γ and IL-2, we pretreated 5 BALB/c mice with either 300 μg mAb 2c or PBS by intravenous injection 24 h before corneal HSV-1 KOS infection." (PMID 25587898, 2015). "Real-time quantitative polymerase chain reaction showed that the expression of TLR3, TLR7, RIG-I, MDA5, IL-1β, IL-2, IL-6, IL-8, IFN-alpha, IFN-beta, IFN-gamma in the lungs was significantly greater than in the respective thymus genes during the early post infection stage." (PMID 26635752, 2015). "Infection of PHA/IL-2 stimulated explants by BaL and non-mac-tropic R5 Env, LN40, was blocked by prior treatment with maraviroc verifying a CCR5-dependent route for infection." (PMID 26055104, 2015). "However, the expression levels of IL-1β, IL-2, IL-8, IFN-alpha, and IFN-gamma were downregulated in the lungs following SS-10 infection at 72 hpi." (PMID 26635752, 2015). "Therefore, understanding how effector and regulatory CD4 T cells listen to IL-2 will unveil pathways and targets to modulate CD4 T cell responses during infection, autoimmunity, and cancer." (PMID 25569154, 2015). "Moreover, levels of IL-2 and IFN-γ also were higher in the primary infection group when infected with L. guyanensis." (PMID 25295285, 2014). "To test whether replication competent HIV-1 induces ISG responses response in IL2/PHA PBMCs, we infected the cells with HIV-1 BaL, and harvested RNA at 12, 24, and 36 hours post infection." (PMID 24404168, 2014). "In the present study, we were not able to detect any increased incidence of fatal infections in the IL-2 plus group." (PMID 23799993, 2013).
infection (continued). "In the spleens, similar to the JaOArS982 infection, the levels of IFN-γ, IL-2 and IL-4 in IL-10 KO and TNF-α KO mice were significantly increased compared with those of WT mice at 7 days pi following JaTH160 infection, whereas the level of IL-5 was decreased in TNF-α KO." (PMID 23940775, 2013). "In contrast, our data suggest that IL-12, but not IL-2, is the key cytokine driving Th1 cell terminal differentiation during infection, presumably through STAT4 positive enforcement of T-bet expression." (PMID 23593003, 2013). "This indicates that the IL-2/pSTAT5 response may be an intermediate step to TH1 expansion and that TH1 biasing occurs only in the context of infection." (PMID 23754944, 2013). "It is noteworthy that under identical experimental conditions used in this study, H-1PV infection of normal IL-2 stimulated human PBMCs failed to activate NK cells as measured through IFN-γ release." (PMID 23902851, 2013). "Six weeks after infection there was still a strong negative correlation between TNF-α+IL-2+ CD4 T cells and the level of bacteria (R2 = 0.92 and 0.57, and p<0.0001 and p = 0.0073 for Ag85B and TB10.4, respectively; fig." (PMID 23977248, 2013). "Finally, to assess the effect of Prostratin and Gö6850 on viral entry directly, IL-2-supplemented MYA-1 CD4+ T-cells were pre-incubated with Prostratin, Prostratin plus Gö6850, Gö6850 or DMSO for 24 h prior to infection with FIV." (PMID 23201205, 2013). "► Prostratin reactivates productive infection from FIV infected, IL-2-depleted feline CD4+ T-cells." (PMID 23201205, 2013). "The recombinant His-tagged GST protein with a predicted pI = 6.7 and recombinant IL-2 (pI = 7.7) did not alter infection and replication of the three viruses, respectively." (PMID 23875025, 2013). "Several cytokines, such as the granulocyte macrophage colony-stimulating factor (GM-CSF), IL-1α, TNF-α, IL-10, IL-17A, IL-2, IL-4 and IL-5, showed a slight but non-significant increase in their serum concentrations upon infection (data not shown)." (PMID 23776551, 2013). "In contrast to conventional T-cells (Tconv), Treg constitutively express CD25 and have STAT5 phosphorylation in the steady-state, arguing for continuous or high frequency intermittent IL-2 signaling in the absence of infection." (PMID 22807926, 2012). "Resistance to infection depends on production of cytokines such as IFN-γ, TNF, IL-2, and IL-12." (PMID 22400039, 2012). "CD4+ T cells were isolated and stimulated with IL-2/PHA, prior to infection with isogenic viruses." (PMID 22537596, 2012). "IL-2 expression did not significantly exceeded background, but, interestingly, did fall significantly below that of uninfected mice at 180 days post-infection." (PMID 22558103, 2012). "PHA/IL-2-treated primary human CD4+ T cells exposed to this recombinant reporter virus reached 1.1, 5.8 and 6.6% of HSA-positive cells after 24, 48 and 72 h post-infection, respectively." (PMID 22876188, 2012). "Based on these observations, we wanted to explore the impact of IL-2 immunotherapy in a model of infection (i.e.: SIV infection of Rhesus macaques) without ART treatment in order to observe only IL-2-induced changes on various immunological parameters." (PMID 23021024, 2012). "In contrast, the expression of other regulatory cytokines such as IL2, IL6 and IL17a (not shown) were not significantly different in resistant and susceptible contexts, nor affected by infection." (PMID 22720048, 2012). "The levels of CD4 cells producing IFN-γ, IFN-γ/TNF-α, or IFN-γ/TNF-α/IL2 all exceeded 1% in BCG vaccinated mice at week 2 of the P. yoelii infection (10 weeks post-BCG immunization) but declined at weeks 7 and 10 post-infection (15 and 18 weeks post-BCG vaccination)." (PMID 22205939, 2011). "Interestingly, infection induced a substantial expansion of TNF-α single positive cells and IL-2/TNF-α double positive cells." (PMID 21720558, 2011).
infection (continued). "In this assay system, PBMC stimulated with phytohemagglutinin (PHA) are cultured with IL-2 before infection in the presence or absence of the test antibodies." (PMID 22069520, 2011). "Infection of macaque PBMCs with PBj-wt virus induced activation of the Raf-MEK-ERK signaling pathway, activation of NF-κB, cell proliferation, expression of T cell surface activation markers and IL-2 secretion in vitro." (PMID 21366921, 2011). "Overexpression of NSP1 and infection with live SARS-CoV strongly increased signalling through the Calcineurin/NFAT pathway and enhanced the induction of interleukin 2, compatible with late-stage immunopathogenicity and long-term cytokine dysregulation as observed in severe SARS cases." (PMID 22046132, 2011). "This enhanced reactivation correlates with increased IL-2R beta expression on memory T cells and IL-2 in the second infection but not with IL-7R alpha expression or increased homeostatic proliferation in the memory phase of the response." (PMID 22039531, 2011). "However, we found that in both SHIV162p3 and SIVmac251 infected macaques, both Th-1 (IL-2, IFN-γ) and Th-2 (IL-4, IL-5, IL-6, IL-10, and IL-13) type cytokines were markedly elevated after infection." (PMID 21464951, 2011). "Finally, following infection with NL4.3Δnef/EGFP of CCL19-treated and IL-2-PHA activated CD4+ T-cells, EGFP expression was 0% and 2% respectively (n = 1)." (PMID 21992606, 2011). "Unlike other pathogens, T. gondii infection does not induce a potent IL-2 response even during the acute phase of infection." (PMID 20520779, 2010). "Egg-positive people had more IL-2 and IL-23 producers compared to egg-negative people, although IL-23 positive people mostly carried light infections." (PMID 21039611, 2010). "IL-2 is a cytokine known to maintain T regulatory cells for self/non-self recognition during infection, as well as stimulate growth, differentiation, and survival of T cells." (PMID 20877574, 2010). "In spite of the transient decrease in antigen-driven IL-2 synthesis, no clinical evidence of infection was noted in any healthy patient." (PMID 20226064, 2010). "The Th2-like cytokines together with anti-cercariae IgM and IgG2 were also higher in egg-negative people, but their association with infection status was modified by the levels of IFN-γ and IL-2 consistent with Th1/Th2 cross-regulation of immune responses." (PMID 21039611, 2010). "Transcripts for several other cytokines (IL-2, IL-4, IL-10, and IL-12) were detected on the array, but their levels did not change significantly during the course of infection." (PMID 17725815, 2007). "Immune exhaustion in P14 cells peaked at day 20 post-clone 13 infection, a time point when P14 cells in spleen and liver had almost no ability to produce IL-2 and TNF-α, and a statistically significant reduction in IFN-γ production was also observed (day 20)." (PMID 17553158, 2007). "PBLs were isolated from three different, healthy, HIV negative donors and activated with PHA and IL-2 prior to infection with 10,000 RT units of the dual-tropic strain of HIV-1p256." (PMID 17625008, 2007). "Additionally, ΔbtpB infection elicited stronger humoral and cellular immune responses in mice, including higher antibody levels, increased levels of Th1 cytokines (such as IFN-γ and IL-2), and enhanced proliferation and activity of CD8+ cells." (PMID 41694393, 2026). "While the authors viewed their findings as hypothesis generating, they concluded that IL-2 lacked clinical value for infection differentiation." (PMID 40647525, 2025). "The evasion of fungal immune control mechanisms with down-regulated Th1 (IFN-γ, TNF-α, and IL-2) and Th17 T cell cytokines (IL-17A) and CXCR3+ T cell chemoattractant chemokine (CXCL10) responses, allows more vigorous replication of Cryptococcus and overwhelming infection." (PMID 39928682, 2025).